BRAF (B-Raf proto-oncogene, serine/threonine kinase)
Diseases named in the same sentence as BRAF in open-access papers (continued):
Sharing a sentence is not in itself a finding about the gene and the disease.
adenoma (continued). "Similarly, BRAF-mutant CRCs are considered to develop from the serrated pathway, where a BRAF mutation typically serves as the initiating genetic event in serrated precursors, unlike conventional adenomas." (PMID 38731846, 2024). "RNF43 mutations have been observed in BRAF-mutant sessile or traditional serrated adenomas, but not in their KRAS-mutant counterparts, suggesting that the alternate modalities of MEK–ERK pathway activation may determine the method by which the Wnt pathway is activated." (PMID 35975243, 2022). "The differences between papillary craniopharyngioma (a non-secreting benign tumour) and ACTH-secreting adenomas with the same underlying genetic driver, BRAF p.V600E, reflect different, yet unknown, roles of oncogenic BRAF in different pituitary cell types leading to tumorigenesis." (PMID 33795686, 2021). "In CRC, BRAF and KRAS alterations typically arise at the adenoma stage of the adenoma‐carcinoma sequence, following an initial APC alteration." (PMID 34584977, 2021). "We have recently curated a series of dysplastic sessile serrated adenomas and shown that 75% of SSAD progress methylate MLH1, are MSI, and thus progress to BRAF mutant MSI cancers." (PMID 29304767, 2018). "Unlike the classic adenoma-carcinoma sequence, where APC inactivation is the initiating event, the serrated pathway is driven by BRAF mutations, with serrated polyps serving as the precursor lesions." (PMID 39119381, 2024). "Notably, conventional adenoma organoids displayed an apoptotic phenotype upon TGFβ treatment, while TGFβ can induce EMT in a BRAF-mutant organoid culture, an in vitro model system for serrated premalignant lesions." (PMID 38731846, 2024). "In the sessile serrated pathway BRAF-mutations are common, sometimes in combination with MSI, while this mutation is almost never present in conventional adenomas." (PMID 37344790, 2023). "BRAF and EGFR-driven tumors were adenomas and adenocarcinomas." (PMID 37828026, 2023). "None of the CD-causing ACTH-secreting adenomas showed the previously reported SNV in the genes encoding USP48, BRAF, BRG1 and CABLES1." (PMID 35563252, 2022). "One major limit of liquid biopsy is the detection of only advanced BRAF- or KRAS-mutated CRC but not BRAF and KRAS wild-type CRC and adenomas." (PMID 32517177, 2020). "Strikingly, none of the samples, including 20 growth hormone-secreting, 20 prolactin-secreting, and 20 non-functioning adenomas, carried either USP48 or BRAF mutations." (PMID 30093687, 2018). "Of 41 BRAF-mutated metanephric adenomas, 33 showed positive VE1 immunostaining (sensitivity 80%, specificity 100%); in all cases we detected p16INK4 expression regardless of BRAF mutation status." (PMID 28903326, 2017).
adenoma (continued). "In contrast to conventional adenoma, mutations in APC are an exception rather than the rule in the developmental pathway of serrated adenoma driven by BRAF." (PMID 26299805, 2015). "The absence of PRDM5 methylation found in conventional adenomas and the low rate seen in BRAF wild type cancers indicates that PRDM5 methylation is not an important event in traditional pathway cancers." (PMID 25613750, 2015). "Studies have investigated the traditional (nonserrated) adenoma-carcinoma sequence and the serrated polyp neoplasia for BRAF and MSI." (PMID 18718023, 2008). "BRAF or KRAS mutations were observed in both non-dysplastic or dysplastic sessile serrated adenomas; most MLH1-deficient sessile serrated adenomas with dysplasia displayed RNF43 mutations less frequent in sessile serrated adenomas with retained MLH1 expression." (PMID 29652830, 2018). "Importantly BRAF V600E mutations were found in 90% of CRC cases with sessile serrated adenoma (SSA) lesions and never in the conventional adenomas." (PMID 23965959, 2013). "Remarkably, this expression profile was associated with the presence of BRAF mutations in the same tissues, strongly supporting our hypothesis that RTC does not arise through the traditional adenoma-carcinoma sequence." (PMID 23425390, 2013). "However recent studies, which used β-catenin immunohistochemistry rather than mutation analysis as a measure of Wnt pathway activation found nuclear β-catenin reactivity in a large part of BRAF mutant advanced (but not early) human adenomas and in carcinomas." (PMID 23845441, 2013). "In addition, in only 4 out of 18 (22%) patients, all of adenomas that each patient carried exhibited the same K-ras/BRAF and RASSF2 status (all exhibited neither K-ras/BRAF mutation nor RASSF2 methylation)." (PMID 17923875, 2007). "Therefore, it is possible that some FDNs with BRAF mutation or MSI-H progress to de novo type cancers (ie, flat or depressed cancers without accompanying adenoma)." (PMID 16404419, 2006). "Although, in principle, oncogenic BRAF can induce hyperplasia, which may accompany induction of OIS, these hyperplastic cells continue to proliferate while accumulating further genetic and epigenetic alterations, and develop into adenomas and then progress to carcinomas." (PMID 35975243, 2022). "Interestingly, the BRAF gene, commonly expressed in cancers arising from the sessile serrated pathway and CMS1 subtypes contained no pks motifs, further supporting the hypothesis that pks + E.coli, may contribute to adenoma-carcinoma pathway CRC development via the action of colibactin." (PMID 39340753, 2024). "It was recently estimated that 75% of sessile serrated adenomas with methylate MLH1 are MSI, and progress to mutant BRAF MSI cancers; however, about 25% do not silence the MLH1 gene and become BRAF mutant MSS cancers." (PMID 29652830, 2018). "Moreover, the association between K-ras/BRAF mutations and RASSF methylation, particularly whether or not they work synergistically or are mutually exclusive, is controversial in CRCs, and has not been sufficiently investigated in adenomas." (PMID 17923875, 2007).
glioblastoma (136 papers, 2011 to 2026). The most malignant astrocytic tumor (WHO grade IV). "All five patients enrolled in the study either had HGGs or glioblastoma with a BRAF V600E mutation that was recurrent following one aspect of therapy (i.e., radiation, immunotherapy, or chemotherapy)." (PMID 40725122, 2025). "The 624-mel cell line contained a mutated BRAF gene (Val600Glu), while both glioblastoma cell lines are characterized by a TERT promotor mutation and a CDKN2C deletion." (PMID 40955425, 2025). "In contrast, the left temporal lobe tumor harbored a BRAF p.Val600Glu (V600E)​​​​​​​mutation, which is a relatively rare event in adult glioblastomas, occurring in approximately 2-3% of cases." (PMID 41473634, 2025). "Postoperative pathology confirmed a high-grade glioblastoma with primitive neuroepithelial and focal spindle cell sarcoma components, characterized by BRAF V600E mutation, WHO grade IV astrocytoma, and MGMT promoter methylation." (PMID 40535548, 2025). "Several studies have investigated the link between BRAF mutations and prognosis in glioblastoma patients, particularly in younger ones." (PMID 38674026, 2024). "The incidence of BRAF mutations diverges according to tumor histology ranging from 1-2% and 2-5% in glioblastoma and astrocytoma to 81-95% in papillary craniopharyngioma." (PMID 36686797, 2022). "We chose two glioblastoma cases with known mutations in BRAF (V600E) and IDH1 (R132H), respectively." (PMID 35937639, 2022). "In contrast, in recurrent glioblastoma patients that respond to PD-1 blockade, there is enriched expression of BRAF and PTPN11 activation mutations." (PMID 34440802, 2021). "The BRAF mutation group had significantly more male patients (64.00% vs. 36.84%; P = 0.046) and a higher occurrence of glioblastoma multiforme (66.00% vs. 31.58%; P = 0.013)." (PMID 33489866, 2020). "Consistent with the original screening dataset, the mesenchymal subtype and BRAF mutations were dominant in the E&F-independent group, and over 90% of proneural glioblastomas belonged to the E&F-dependent group." (PMID 32120790, 2020). "The BRAF mutation group had significantly more male patients (64.00% vs. 36.84%; P = 0.046) and a higher occurrence of glioblastoma multiforme (66.00% vs. 31.58%; P = 0.013) compared to those in the other group." (PMID 33489866, 2020). "Recently, it was reported that BRAF (which encodes a serine/threonine protein kinase) mutation was closely related to improved survival in glioblastoma." (PMID 31261921, 2019). "Although recent studies show that CSF is more representative of the original tumor genetic features than plasma in Glioblastoma patients, we cannot evaluate it, as we only have five paired samples whose solid biopsies have been analyzed for BRAF mutation." (PMID 31881643, 2019). "The BRAF V600E mutation has also been documented in a morphological variant of glioblastoma (epithelioid glioblastoma)." (PMID 29098416, 2018). "Eighty percent (12/15) of BRAF mutated glioblastomas concurrently harbored CDKN2A homozygous deletion, compared with 26.4% (19/72) of BRAF wild-type glioblastomas (p = 0.0002)." (PMID 26452024, 2016). "Comparing the age between BRAF mutated and BRAF wild-type glioblastomas, patients with mutated BRAF were younger than those with wild-type." (PMID 26452024, 2016). "Dahiya and colleagues evaluated the BRAF status in 39 adult glioblastomas and identified 7.7% (three cases) possessing the mutation." (PMID 26452024, 2016). "In summary, our study demonstrates the clinical values of stratifying young adult glioblastomas with BRAF, H3F3A and IDH1 mutations, which has important implications in refining prognostic classification of glioblastomas." (PMID 26452024, 2016). "In univariate analysis, the median overall survival of patients with BRAF mutated glioblastomas was 43.2 months and those with wild-type BRAF was 13.6 months (p = 0.032)." (PMID 26452024, 2016).
glioblastoma (continued). "Further study should be conducted to evaluate the clinical value of concurrent BRAF and TERTp mutations in young adult glioblastomas." (PMID 26452024, 2016). "Given the potential clinical utility in prognostication and treatment selection, BRAF mutational testing, either by direct sequencing or immunohistochemistry, should be conducted in glioblastomas of young patients." (PMID 26452024, 2016). "Robinson and colleagues recently reported a case of BRAF mutated pediatric glioblastoma treated by BRAF inhibitor vemurafenib and showed complete response." (PMID 26452024, 2016). "In this study, we sought to stratify young adult glioblastomas by BRAF, H3F3A and IDH1 mutations and examine the clinical relevance of the biomarkers." (PMID 26452024, 2016). "The mean ages of BRAF mutated glioblastomas and BRAF wild-type glioblastomas were 22.3 years and 25.5 years, respectively (p = 0.013)." (PMID 26452024, 2016). "The median overall survival was 43.2 months for BRAF mutated glioblastomas and 13.6 months for BRAF wild-type glioblastomas." (PMID 26452024, 2016). "Although only 2.9% (3/104) of patients harbored concurrent BRAF-V600E and TERTp mutation, this subgroup accounted for 18.8% (3/16) of BRAF mutated glioblastomas of young adults." (PMID 26452024, 2016). "In the study by Schindler and colleagues examining 1,320 nervous system tumors, BRAF mutation was detected in less than 2% of adult glioblastomas investigated." (PMID 26452024, 2016). "Apart from the potential prognostic value, BRAF-V600E mutation also served as a novel therapeutic target in this subset of glioblastomas." (PMID 26452024, 2016). "Further comparison of patient age between the mutually exclusive molecular subgroups also revealed that BRAF mutated glioblastomas were younger than IDH1 mutated glioblastomas (mean age 22.3 years vs 27.9) (p = 0.0008, One-way ANOVA)." (PMID 26452024, 2016). "Knobbe and co-workers investigated 94 glioblastomas and identified three cases (3.2%) harboring BRAF mutation." (PMID 26452024, 2016). "Based on the focal features of epithelioid glioblastoma multiforme, a variant previously reported to have a high proportion of BRAF abnormalities, BRAF V600E testing was performed on material extracted from the paraffin embedded tissue." (PMID 24725538, 2014). "In line with this mutation frequency, review of 62 standard glioblastoma cases that had undergone clinical testing at MGH using SNaPshot mutation profiling identified only one case with a BRAF V600E mutation (1.6%)." (PMID 21479234, 2011). "In total, BRAF V600E mutation in standard glioblastomas has been reported in approximately 1.7% of cases (5 of nearly 300 cases)." (PMID 21479234, 2011). "BRAF V600E mutations were identified in only 2 of 71 (2.8%) glioblastoma (GBM) analyzed, including 1 of 9 (11.1%) giant cell GBM (gcGBM)." (PMID 21479234, 2011). "In contrast, BRAF mutations are relatively uncommon in IDH-wildtype glioblastomas." (PMID 41473634, 2025). "Among BRAF-associated glioblastomas, three distinct mutation classes have been described." (PMID 40725122, 2025). "This suggests that even in highly aggressive conditions, such as multifocal glioblastoma, the presence of certain mutations, such as BRAF p.Val600Glu (V600E)​​​​​​​, could favorably influence tumor behavior and open the door to personalized treatment options." (PMID 41473634, 2025). "In human brain tumours, BRAF V600E mutations are seen in 5% of posterior fossa pilocytic astrocytomas, approximately one third of gangliogliomas and nearly 70% of pleomorphic xanthoastrocytomas, and a small proportion of glioblastomas." (PMID 39324445, 2024). "This is the only BRAF mutation found in glioblastoma, albeit at a very low prevalence." (PMID 37857607, 2023). "Interestingly, MAPK pathway alterations such as PTPN11 and BRAF mutations are enriched in patients who respond to anti-PD-1 therapy, although these represent only a small proportion of patients with glioblastoma." (PMID 33396284, 2020).
glioblastoma (continued). "Unfortunately, only a small fraction of all glioblastomas have BRAF mutations (~3%) and could potentially benefit from these approaches." (PMID 33396284, 2020). "While glioblastomas tend to have a low frequency of BRAF mutations, BRAF inhibitors might potentially be useful in this population subset." (PMID 33237934, 2020). "Moreover, we established a cell line retaining the BRAF V600E mutation, which morphologically resembled the epithelioid glioblastoma, and were able to evaluate the efficacy of combined treatment." (PMID 31345255, 2019). "Pediatric glioblastoma have BRAF mutations in approximately 10–20% of cases." (PMID 31466300, 2019). "Furthermore, in some series, all BRAF V600E mutated glioblastomas showed distinct epithelioid features of the tumor cell morphology." (PMID 31181803, 2019). "Glioblastoma in adults have BRAF V600E mutations only infrequently (~3%)." (PMID 31466300, 2019). "BRAF V600E mutations have been described in a wide variety of lesions: 80% of pleomorphic xanthoastrocytomas 33% of the gangliogliomas, 23% of the diffuse astrocytomas, 10% of the glioblastomas being more frequent in tumors located in the cerebral cortex." (PMID 30558563, 2018). "In 17 of 22 cases (5.1%) without a conclusive histological diagnosis NGS resulted in a molecular tumor diagnosis (77.3%): 3 were diagnosed with oligodendroglioma (13.6%), 2 with astrocytoma (9.1%), 11 with glioblastoma (50.0%) and 1 with a BRAF-mutated tumor (4.5%)." (PMID 30470264, 2018). "Epithelioid glioblastomas harbor the BRAF-V600E mutation in about half of all cases." (PMID 28532485, 2017). "Notably, with the exception of three BRAF mutated glioblastomas concurrently harboring TERTp mutation, BRAF, H3F3A, IDH1, TERTp mutations and EGFR amplification were mutually exclusive." (PMID 26452024, 2016). "BRAF mutated glioblastomas exhibited better prognosis than those with wild-type BRAF (p = 0.032)." (PMID 26452024, 2016). "The BRAFV600E mutation is rare in glioblastoma multiforme, and the authors suggest that BRAF inhibitors may be particularly effective in pediatric CNS tumors subtypes that express BRAFV600E more prevalently." (PMID 26525348, 2015). "Therefore, we performed NGS analysis to determine the mutational status of BRAF of 13 glioblastomas (GBMs) (11 primary and 2 secondary cases) and detected one tumor harboring the BRAF V600E mutation." (PMID 25885250, 2015). "Depending on the results of additional clinical studies, determination of BRAF mutation status may become clinically relevant also for primary brain tumors such as glioblastoma in the future." (PMID 22385786, 2012). "BACKGROUND: Epithelioid glioblastoma (GBM) is characterized by its highly aggressive behavior and the presence of the BRAF V600E mutation." (PMID 41469702, 2025). "Among glioblastoma (GBM), BRAF V600E mutation can be found in 1–8% of patients, whereas a higher mutation rate is shown in patients below the age of 30 years (20%)." (PMID 35158978, 2022). "For example, particularly relevant to GBM, the variant “epithelioid glioblastoma” is noted to be characterized frequently by BRAF V600E mutations, a factor, which has generated interest regarding its relationship to pleomorphic xanthoastrocytoma." (PMID 29312129, 2017). "Notably, among the 16 BRAF mutated glioblastomas, 11 cases had operation record and total resection could be achieved in all cases (p = 0.013), suggesting BRAF mutated glioblastomas were more amendable to surgical resection." (PMID 26452024, 2016). "Encouragingly, there have been individual case reports where dabrafenib has shown a favorable clinical response in pediatric patients with BRAF-V600E mutant glioblastoma (epithelioid glioblastoma)." (PMID 40113789, 2025).